CCL2 (C-C motif chemokine ligand 2)
Diseases named in the same sentence as CCL2 in open-access papers (continued):
Sharing a sentence is not in itself a finding about the gene and the disease.
dengue (continued). "High levels of pro-inflammatory cytokines and chemokines, including TNF-α, IL-6, IL-8, CCL2/MCP-1 and IFN-γ, have been reported in patients with severe dengue disease." (PMID 21206747, 2010). "Recent clinical studies in endemic areas describe a correlation between dengue disease outcome and levels of CC chemokines, including CCL4/MIP1-β and CCL3/MIP1-α, both ligands for the CCR1 receptor, and for CCL2/MCP-1, the ligand for CCR2." (PMID 21206747, 2010). "Moreover, serum levels of IL-15, CCL-2, CXCL-10, and CXCL-11 correlated with dengue severity in humans." (PMID 40934228, 2025). "In dengue infection, platelet-monocyte aggregation was induced in dengue patients and the aggregate formation could enhanced the production of cytokines and chemokines by monocytes including TNF-α, IL-1b, IL-8, and CCL2/MCP-1." (PMID 30744623, 2019). "As in our previous studies, the dengue patients had high plasma levels of the cytokines TNF-α (p < 0.001), IL-6 (p = 0.005), IL-10 (p < 0.001) and, IL-18 (p = 0.001) and the chemokines CXCL8/IL-8 (p < 0.001), CCL2/MCP-1 (p < 0.001), CXCL10/IP-10 (p = 0.001) compared to healthy controls." (PMID 34578370, 2021). "Levels of the chemokine C-C ligands 2, 3 and 4 (CCL2, CCL3 and CCL4) have been correlated with severe dengue disease in humans in several studies, and mice lacking these chemokines have reduced lethality and milder disease during dengue infection." (PMID 28644404, 2017).
Anxiety (57 papers, 2009 to 2026). Intense feelings of nervousness, tension, or panic often arise in response to interpersonal stresses. "In summary, our study establishes the association between high myopia and anxiety for the first time and highlights the CCL2-mediated inflammatory pathogenesis as its underlying mechanism." (PMID 37699875, 2023). "Compared with wild-type highly myopic mice, Ccl2-deficient highly myopic mice displayed significantly reduced anxiety levels during OFT and EPM tests, in both dark and light conditions, which was also confirmed by the Vogel test." (PMID 37699875, 2023). "Our results establish the association between high myopia and anxiety, and implicate the CCL2-mediated inflammatory pathogenesis as an underlying mechanism." (PMID 37699875, 2023). "In this study, we confirmed higher risk of anxiety in highly myopic patients and mice, accompanied by higher CCL2 expression and monocyte levels in their blood." (PMID 37699875, 2023). "Together, our findings confirm the association between anxiety and high myopia for the first time, and demonstrate that CCL2-mediated inflammatory pathogenesis is the underlying mechanism of this anxiety." (PMID 37699875, 2023). "The duration in the center of the open field was negatively correlated with the CCL2 level in the blood of the highly myopic mice (r = –0.876, P = 0.0221), suggesting that higher anxiety level is associated with higher blood CCL2 level in mice." (PMID 37699875, 2023). "In healthy hospital workers, anxiety scores were found inversely associated with levels of CCL2, CCL5, CCL11, and IL-6." (PMID 34863117, 2021). "Ccl2 deficiency or CCL2 blockage could substantially alleviate high myopia-related anxiety, probably by attenuating the infiltration of monocytes/macrophages and disruption of BOB/BBB." (PMID 37699875, 2023). "Conversely, Ccl2-deficient highly myopic mice exhibit attenuated ocular and brain infiltration of monocytes/macrophages, reduced disruption of the blood–ocular barrier and blood–brain barrier, and less anxiety." (PMID 37699875, 2023). "To examine the role of CCL2 in high myopia-related anxiety, we used a Ccl2-deficient mouse model." (PMID 37699875, 2023). "CCL2 has been linked to important alcohol-related behaviors, drinking, and alcohol withdrawal-induced anxiety-like behavior making it an important candidate target for the treatment of alcohol use disorder." (PMID 33192326, 2020). "Another explanation would be that too much or too little CCL2 causes anxiety-like behavior." (PMID 33192326, 2020). "This article sought to demonstrate whether loss of CCL2 solely in CeA neurons would alter alcohol withdrawal-induced anxiety-like behavior and whether this effect is related to changes in anti-inflammatory chemokines." (PMID 33192326, 2020). "For example, injection of TNF-α into the ventricles causes elevations in mean arterial pressure and repeated microinjections of TNF-α and Ccl2 into the amygdala prior to prolonged alcohol exposure have been associated with an exaggerated anxiety-like response during withdrawal." (PMID 22626265, 2012). "However, when the CCL2 depletion was paired with a mild withdrawal from chronic alcohol that by itself did not cause anxiety-like behavior, the combination caused a significant anxiety-like response." (PMID 33192326, 2020). "The early onset TSD mouse model Hexa−/−Neu3−/− mice demonstrated a high level of anxiety, along with elevated levels of Ccl2, Ccl3, Ccl4, Cxcl10." (PMID 39905541, 2025). "Here, we report that highly myopic patients exhibit greater anxiety, accompanied by higher CC chemokine ligand 2 (CCL2) and monocyte levels in the blood." (PMID 37699875, 2023). "Together with the elevated inflammatory cytokines identified in the blood of highly myopic subjects, this suggests a CCL2-mediated inflammatory pathogenesis for high myopia-related anxiety." (PMID 37699875, 2023).
Anxiety (continued). "We previously reported that LPS-induced anxiety-like behavior in adult male mice positively correlated with IL-6 and CCL2 levels in the plasma and chemokine (CXCL10 and CCL2) expression in the brain." (PMID 36698151, 2023). "Evidence has suggested a role of blood–brain barrier (BBB) disruption in CCL2-related psychiatric disorders, including anxiety, depression, and social avoidance." (PMID 37699875, 2023). "Substantial alleviation of high myopia-related anxiety can also be achieved with the administration of CCL2-neutralizing antibodies." (PMID 37699875, 2023). "To investigate the role of CCL2 elevation in high myopia-related anxiety, we observed the infiltration of monocytes/macrophages in the eye and brain with flow cytometry." (PMID 37699875, 2023). "After controlling clinical measures for age + gwk + BMI, chemokines such as IL-8/CXCL8, MCP-1/CCL2 and MIP-1β/CCL4 were found associated with high scores for anxiety (p < 0.05) in the ANX group." (PMID 34863117, 2021). "In an animal model, knock-out of Ccl2 prevented prenatal stress induced deficits in sociability and anxiety-like behavior in the offspring." (PMID 34446099, 2021). "MCP-1/CCL2 appears to be dysregulated in stress-inducing anxiety-like behaviors in humans and rodents." (PMID 34863117, 2021). "Changes in CCL2 in the neurons of the CeA have been correlated with changes in alcohol withdrawal-induced anxiety-like behavior." (PMID 33192326, 2020). "Given the importance of CCL2 levels in the CeA in anxiety-like behavior, it is important to identify the upstream pathways that regulate CCL2." (PMID 33192326, 2020). "When a herpes simplex virus (HSV) vector was used to knockdown CCL2 mRNA in neurons of the central nucleus of the amygdala (CeA) in rats experiencing multiple withdrawals from low dose ethanol, anxiety-like behavior appeared in the social interaction task." (PMID 33192326, 2020). "Ccl2 and Nfkbia were also downregulated in the amygdala, a brain area involved in emotionality including anxiety." (PMID 30036185, 2018). "Elevated ocular CCL2, driven by highly myopic visual stimulation, may be the initiator of high myopia-related anxiety." (PMID 37699875, 2023). "Further investigations with Ccl2-deficient mice and mice treated with CCL2-neutralizing antibodies showed that high myopia-related anxiety could be substantially attenuated by the inhibition of CCL2." (PMID 37699875, 2023). "In the highly myopic mouse model, we detected a significant increase of Ly6C+ monocytes in the eyes and anxiety-related brain areas including BLA and ventral hippocampus, which could be attenuated by Ccl2 deficiency." (PMID 37699875, 2023). "To further explore the role of CCL2 in the anxiety of high myopes, we analyzed human blood samples with a suspension cytokine array and identified significantly higher levels of CCL2 in the blood of highly myopic patients (30.04 ± 14.19 pg/mL vs 24.64 ± 14.63 pg/mL in the control, P = 0.0073)." (PMID 37699875, 2023). "Finally, CRF like CCL2 can induce anxiety-like behavior in combination with subthreshold alcohol withdrawal." (PMID 33192326, 2020). "Indeed, the sociability deficits and anxiety-like behavior observed in WT adult offspring were ameliorated in CCL2−/− offspring." (PMID 32546752, 2020). "Altogether these actions may represent a neuronal CCL2 circuit that could be involved in behaviors such as anxiety." (PMID 33192326, 2020). "Being localized in CeA projection neurons opens up the possibility that CCL2 made in CeA neurons could have effects on anxiety-like behavior by being released in other brain regions." (PMID 33192326, 2020). "Here, we provide evidence of the critical role of microbes and CCL2 in mediating fetal brain inflammation and placental tryptophan and 5-HT availability following maternal stress and leading to aberrant sociability and anxiety-like behavior in adult offspring." (PMID 32546752, 2020).
Anxiety (continued). "The combination of alcohol withdrawal and CCL2 knockdown decreased CX3CL1 and may alter pro-inflammatory/anti-inflammatory balance, and thus highlights the potential importance of CCL2 and CCL2/CX3CL1 balance in anxiety." (PMID 33192326, 2020). "Chemokines such as chemokine (C-C motif) ligand 2 (CCL2) play a role in several behaviors, including anxiety-like behavior, but whether neurons are an important source of CCL2 for behavior and how neuronal CCL2 may work to affect behavior are still debated." (PMID 33192326, 2020). "Interestingly, the previous study found that acute ICV injection of CCL2 increased withdrawal-induced anxiety-like behavior while the present study found that more chronic depletion of CCL2 in CeA neurons had the same effect." (PMID 33192326, 2020). "According to this interpretation under normal conditions, CX3CL1 could balance CCL2 and function as an inhibitor of anxiety." (PMID 33192326, 2020). "However, the role of CCL2 extends beyond alcohol-related behaviors and is related to other types of anxiety." (PMID 33192326, 2020). "Therefore, we speculated that CCL2 might also play an essential role in high myopia-related anxiety via inflammatory pathogenesis." (PMID 37699875, 2023). "Recent studies have shown that CC chemokine ligand 2 (CCL2), which regulates the recruitment of peripheral mononuclear cells, plays a critical role in anxiety-related psychiatric disorders, such as social defeat stress, alcohol-withdrawal-induced anxiety, and suicidal tendencies." (PMID 37699875, 2023). "Our data show that high myopes with anxiety presented with even higher levels of blood CCL2 than those with no anxiety, and the positive association between the anxiety scores and blood CCL2 levels is similar to the findings for post-traumatic stress disorder and generalized anxiety disorder." (PMID 37699875, 2023). "Mechanistic studies showed that highly myopic visual stimulation increased CCL2 expression in the eyes, which led to increased monocyte/macrophage infiltration in the eyes and brain, BOB/BBB disruption, and consequently more anxiety in mice." (PMID 37699875, 2023). "Collectively these results confirm the importance of neuronal CCL2 in behavior and highlight the need for further exploration of the CCL2/CCR2 neuronal circuits that exist in brain regions vital to anxiety." (PMID 33192326, 2020). "This is further supported by our finding that projection neuron from the CeA to regions related to anxiety, like the BNST and the VPAG, contain CCL2." (PMID 33192326, 2020). "To corroborate our hypothesis, we first verified the increased anxiety level in highly myopic patients using the Hamilton Anxiety Scale (HAMA), which was positively correlated with the CCL2 and monocyte levels in their blood." (PMID 37699875, 2023). "Similarly, chemokines such as ENA-78/CCL5, GROα/CXCL1, MCP-1/CCL2, and TARC/CCL17 were increased in women displaying high anxiety levels." (PMID 34863117, 2021). "Anxiety-like behavior increased in rats that received ED and the HSV vector for CCL2 siRNA compared with rats that received only ED or only the HSV vector for CCL2 siRNA (ED-CCL2 vs. CD-CCL2 p < 0.05; ED-CCL2 vs. ED-Sc p < 0.05)." (PMID 33192326, 2020). "PNS offspring also exhibited deficits in sociability and anxiety-like behavior that were absent in CCL2−/− PNS offspring." (PMID 32546752, 2020). "Together, our data indicate that PNS results in social- and anxiety-related behavioral abnormalities in the offspring, which are ameliorated in the absence of CCL2." (PMID 32546752, 2020). "Indeed, it was found that the increase in CX3CL1 caused by CCL2 knockdown was completely reversed following withdrawal from alcohol suggesting that the loss of both CCL2 and CX3CL1 below functional levels may be responsible for the increase in anxiety-like behavior in this experimental group." (PMID 33192326, 2020).
Anxiety (continued). "Additionally, CRF and a CRFR1 antagonist also control alcohol withdrawal-induced anxiety-like behavior —perhaps through CRF control of the activated TLR4 signal which controls CCL2." (PMID 33192326, 2020). "While upregulation of CCR2 in the AMG associated with neuropathic pain has not previously been reported, an overexpression of CCL2 in the CeA of mice with partial sciatic nerve ligation (PSNL) that exhibited anxiety-like behavior and hypersensitivity to mechanical stimuli has been demonstrated." (PMID 40244217, 2025). "We then injected C57BL/6J mice with CCL2-neutralizing antibody during high myopia modeling and found that these mice also displayed substantially less anxiety in OFT and EPM tests, suggesting that high myopia-related anxiety can be alleviated by either Ccl2-knockout or CCL2 blockage." (PMID 37699875, 2023). "Thus, regarding high myopia-related anxiety, the disruption of the blood–ocular barrier (BOB) and the BBB may also be involved in the CCL2-mediated inflammation in the eyes and the defective emotional responses in the brain." (PMID 37699875, 2023).
chronic kidney disease (56 papers, 2012 to 2025). Impairment of the renal function secondary to chronic kidney damage persisting for three or more months. "Ccl2 has also been implicated as a key mediator of chronic kidney disease in animal models as well as in humans." (PMID 29872089, 2018). "Again, FSTL1 is not the only ligand to increase expression of these genes in vivo, but we were able to see strong correlations between Fstl1 mRNA levels and the mRNA levels of Ccl2 and Tnfa, two cytokines implicated in the progression of chronic kidney disease." (PMID 34502419, 2021). "Recent studies have shown that curcumin can alleviate inflammation in chronic kidney disease (CKD) by reducing chemokine 2 (CCL-2), interferon-γ (IFN-γ), and interleukin-4 (IL-4) and regulating lipid peroxidation." (PMID 41170356, 2025). "In a group of patients with chronic kidney disease, the levels of albuminuria correlated closely with urinary CCL2 excretion." (PMID 34369383, 2021). "Glomeruli and renal tubule injury in chronic kidney disease (CKD) is reported to involve induction of macrophage activation through the CCL2/CCR2 axis." (PMID 33159802, 2021). "CCL2 is overexpressed in patients with chronic kidney disease." (PMID 38794167, 2024). "The aim of this studywas to evaluate RAAS molecules and chemokine (C-C motif) ligand 2 (CCL2) in82 patients with chronic kidney disease (CKD)." (PMID 34251390, 2022). "More recently, by studying a group of pediatric patients at stages 2 to 4 of chronic kidney disease (CKD), we detected higher levels of urinary CCL2/MCP-1 in patients with FSGS than in cases of uropathies at the same stage of CKD." (PMID 24692841, 2014). "Overexpression of CCL2 and CCL5 can play a key role in progression of fibrosis in chronic kidney disease." (PMID 38794167, 2024). "In addition, an increase in chemokine ligand 2 (CCL2) mRNA content was observed in EVs from kidneys of mice exposed to lipopolysaccharide and in uEVs of rats with 5/6 nephrectomy, experimental models of AKI and chronic kidney disease (CKD), respectively." (PMID 32351960, 2020).
diabetic retinopathy (56 papers, 2008 to 2025). "In addition, the A-2518G CCL2 gene polymorphism, directly associated with increased CCL2 expression, is indicated as a potential risk factor for diabetic retinopathy." (PMID 25329075, 2014). "Furthermore, the A-2518G CCL2 gene polymorphism, shown to be a potential risk factor for patients with diabetic retinopathy, strengthens the evidence for a role of this chemokine in diabetic macular edema." (PMID 25329075, 2014). "As CD40-driven ICAM-1 expression and CCL2 production are essential for the pathogenesis of inflammatory diseases, including diabetic retinopathy, advanced glycation end products-mediated CD40 dysregulation is functionally relevant." (PMID 40005847, 2025). "Another study reported upregulation of CD40, TRAF2, and TRAF6 in patients with diabetic retinopathy, where CD40 was associated with the expression of pro-inflammatory molecules such as intercellular adhesion molecule 1 (CD54), CCL2, and TNFα." (PMID 38554187, 2024). "AGE-mediated CD40 upregulation was functionally relevant since it enhanced CD40-driven expression of ICAM-1 and production of CCL2, events central to the pathogenesis of inflammatory disorders, including diabetic retinopathy." (PMID 38474393, 2024). "In previous ocular studies, overexpression of the CCL2 was involved in the pathogenesis of diabetic retinopathy." (PMID 36798135, 2023). "In the retina, induction of CCL2 has been widely featured in various eye diseases including age-related macular degeneration, diabetic retinopathy, and retinopathy of prematurity." (PMID 35005021, 2021). "The vitreous levels of CCL2 have been reported to be consistently increased in patients with diabetic retinopathy –17." (PMID 25329075, 2014). "Our findings in the retinas of diabetic animals are consistent with similarly increased levels of CCL2 seen in the vitreous of patients with diabetic retinopathy." (PMID 25329075, 2014). "Concentrations of CCL8, CCL2, CXCL8 and CXCL10 may be associated with diabetic eye disease, especially in diabetic retinopathy and diabetic macular edema." (PMID 38790059, 2024). "In parallel, the intraocular cytokine milieu in diabetic retinopathy consistently shows elevated levels of IL−6, IL−8 (CXCL8), and CCL2 (MCP−1)." (PMID 41394857, 2025). "The role of several cytokines such as IL-6, IL-8, MCP-1/CCL2, and VEGF is well-known in diabetic retinopathy (DR)." (PMID 38338843, 2024). "CCL2 and CXCL8 were elevated in eyes with diabetic retinopathy (but not in the diabetic patients without retinography group) compared to non-diabetic controls, in keeping with reports from previous studies." (PMID 22511846, 2012). "Importantly, diabetic Cd40−/− mice are protected from retinal upregulation of intercellular adhesion molecule 1 (ICAM-1), TNF-α, IL-1β, nitric oxide synthase 2 (NOS2) and C-C motif chemokine ligand 2 (CCL2) and do not develop diabetic retinopathy." (PMID 35920844, 2022).